CD4 (CD4 molecule)
Diseases named in the same sentence as CD4 in open-access papers (continued):
Sharing a sentence is not in itself a finding about the gene and the disease.
sarcoidosis (continued). "The immunology of sarcoidosis and CBD are quite similar, based on a predominance of CD4+ T cells in the lung, a Th1 polarized immune response, and a pathologic hallmark of granulomatous inflammation." (PMID 32256501, 2020). "The Janus kinase (JAK)-STAT pathways have also been shown to be active in sarcoidosis, especially in the TH1 and TH17 CD4+ T-cell subtypes." (PMID 33036432, 2020). "Similarly, our findings in sarcoidosis CD4 naïve T cells suggest they may be effectively targeted by nintedanib, a multi-tyrosine kinase inhibitor approved for use in idiopathic pulmonary fibrosis that targets the JAK/STAT pathway and reduces the effects of TGFβ signaling." (PMID 33363531, 2020). "In sarcoidosis TREM-1 expression decreased with changes of HRCT image, decrease in CD4/CD8 ratio and decrease in DLCO." (PMID 32508528, 2020). "The resulting increase in the CD4/CD8 ratio, in particular when > 3.5, has been suggested to be of help in diagnosing sarcoidosis." (PMID 32111204, 2020). "In our study, CD4/CD8 ratios in blood and BAL were found to be 1.32 and 3 in patients with sarcoidosis, respectively." (PMID 33062080, 2020). "Out of 749 patients with sarcoidosis, 268 subjects were identified with BALF CD4+ Vα2.3+ T-cells expansions." (PMID 32111204, 2020). "Thus, the evaluation of CD103 expression in BALF CD4+ T lymphocytes may be a reliable tool in the sarcoidosis diagnostic work-up, regardless of the CD4+/CD8+ ratio." (PMID 31466346, 2019). "On bronchoalveolar lavage (BAL) fluid with lymphocytosis (15%) and increased ratio of CD4 to CD8 (>3.5:1), the specificity for the diagnosis of sarcoidosis approaches 95%." (PMID 31731423, 2019). "We investigated the ratio of T-lymphocytes/B-lymphocytes, CD4/CD8 T-lymphocytes and regulatory T cells (Treg)/CD4 T-lymphocytes in affected lymph nodes of sarcoidosis patients." (PMID 30452447, 2018). "Microarray analysis of sarcoidosis PBMC and CD4+ T cells revealed a positive relationship between BATF and PD-1." (PMID 29234685, 2017). "Ten (77%) of those with sarcoidosis in our study had low CD19 counts, nine (69%) had low CD3 counts, and eight (62%) had low CD4 counts." (PMID 29371544, 2017). "The majority of patients (n = 10) with sarcoidosis were at chest X-ray stage I. The percentages of specific T cell populations, including CD3, CD4, and CD8, were similar in the sarcoidosis and TB groups." (PMID 28143482, 2017). "The comparison within the 3 groups showed the sarcoidosis group has the highest average HEC number (41.33) and average HEC ratio (66.18%), while the CD4+ group has the lowest average HEC number (7.85) and average HEC ratio (15.17%)." (PMID 29163767, 2017). "We calculated the Gini coefficient of CD4+ group, CD8+ group and sarcoidosis tissue group and found the tissue group with the highest Gini coefficient, CD4+ group the lowest and medium CD8+ group." (PMID 29163767, 2017). "A BAL CD4:CD8 lymphocyte ratio of >3.5:1 is a well-validated marker, highly specific for sarcoidosis." (PMID 27878437, 2017). "We observed evidence of T cell exhaustion in sarcoidosis BAL and PBMC, a phenotype mediated, at least in part, by PD-1 upregulation in the population of CD4+ cells." (PMID 29234685, 2017). "In the present study, we conducted immunology repertoire study of pulmonary sarcoidosis T cells in CD4+, CD8+ PBMC and sarcoidosis tissue to reveal the immunological affect in sarcoidosis." (PMID 29163767, 2017). "Therefore, we were interested in identifying the different CD4+ helper T cells that might mediate the pathogenesis of relapsing and stable pulmonary sarcoidosis to detect a promising biomarker related to the relapse of sarcoidosis." (PMID 26845566, 2016). "Total CD3+ as well as CD4+ and CD8+ PBTLs obtained from PBMCs of the patients with sarcoidosis displayed lower mean fluorescence intensity (MFI) of AUF1 (p≤0.02) and HuR (p≤0.03) than those from healthy controls." (PMID 27575817, 2016).
sarcoidosis (continued). "The expression of AUF1 protein was consistently down-regulated in both CD4+ and CD8+ PBTLs from our patients with sarcoidosis compared to those from healthy controls." (PMID 27575817, 2016). "We found that PPARβ/δ mRNA expression is higher in total BAL cells in non-LS patients compared to LS patients and HC, and a tendency towards higher PPARδ protein expression in blood CD4+ and CD8+ T cells in sarcoidosis patients." (PMID 25969669, 2015). "When the CD4/CD8 lymphocyte ratio in bronchoalveolar lavage (BAL) fluid (BALF) is greater than 3.5, the sensitivity and specificity for the diagnosis of sarcoidosis are 53% and 94%, respectively, with a positive predictive value of 76%." (PMID 26271927, 2015). "CD4+ and CD8+ T cell subsets and AMs detected in the BAL of patients with inactive sarcoidosis were superimposable to those observed in controls." (PMID 26240517, 2015). "It was not also possible to obtain a significant correlation between lymphocyte immune-phenotyping results of BAL (with particular reference to CD4+/CD8+ ratio) and the SUVmax⁡ values of patients with sarcoidosis." (PMID 25866780, 2015). "We surveyed the TCR Vβ usage in CD4+ and CD8+ T cells in bronchoalveolar lavage (BAL) cells and peripheral blood mononuclear cells (PBMC) from 15 HLA-typed Scandinavian sarcoidosis patients." (PMID 24656074, 2014). "In the present study, CD4+ T cells from BALF are studied, which are more directly involved in the immunologic process of sarcoidosis than peripheral blood cells." (PMID 24882950, 2014). "In this study, we investigated the proportion of CD4+ T cell subsets expressing FoxP3 and, upon stimulation, IL17 or IFN-γ in patients with sarcoidosis, other DPLDs, and healthy control subjects." (PMID 24882950, 2014). "The CD4/CD8 ratio, HLA-DR+ CD4+, and HLA-DR+ CD8+ T cells were significantly higher in patients with sarcoidosis compared to HC (P < 0.0001, P < 0.0001, and P < 0.0001, resp)." (PMID 24882950, 2014). "Compared to healthy control subjects, the Th17 cell fraction of CD4+ T cells was 45% lower (P = 0.011) and the proportion of Th17 cells positive for IFN-γ was over twofold greater (P = 0.0005) in sarcoidosis." (PMID 24882950, 2014). "Fractions of both Th17 cells and FoxP3+ CD4+ T cells were lower in sarcoidosis than in HC, and we found a highly elevated ratio between IFN-γ+ fractions of Th17 cells and FoxP3+ CD4+ T cells, possibly indicating an immune cell imbalance." (PMID 24882950, 2014). "BALF of sarcoidosis patients showed a higher lymphocyte total cell count and CD4/CD8 T ratio with higher CD4 and lower CD8 T lymphocyte subset frequencies, but comparable CD3 T and B lymphocyte, NK cell, and nonbiased NKT cell frequencies." (PMID 25142143, 2014). "Recent studies have found a predominant increase of IL-17A+CD4+ memory T cells in the peripheral blood and bronchoalveolar lavages of pulmonary sarcoidosis patients, strongly suggesting (Th17) cells may play an important role in the pathogenesis of sarcoidosis." (PMID 24885153, 2014). "It has also been shown that upon stimulation, compared with controls, there are increased numbers of CD4+IFNγ+ cells in both BALF and induced sputum of patients with sarcoidosis." (PMID 26464848, 2013). "High levels of IL-17+/CD4+ T lymphocytes have been found in the BALF and granulomas of sarcoidosis patients, particularly in patients with active disease." (PMID 26464848, 2013). "Under unstimulated conditions, the difference in the percentages of IL-4 and IFNγ secreting CD4+ lymphocytes in BALF and peripheral blood of sarcoidosis patients is insignificant." (PMID 26464848, 2013). "After stimulation, more T cells express TH1 than TH2 cytokines in both the BALF and peripheral blood of sarcoidosis patients and more CD4+ T cells in BALF express TH1 receptors (CXCR3, CCR5, IL-12R and IL-18R) than CD4+ T cells in the peripheral blood." (PMID 26464848, 2013).
sarcoidosis (continued). "Third, a limited clonality of CD4+ T cells, expressing the AV2S3 T cell receptor, was demonstrated within the lungs of HLA-DRB1*03 positive sarcoidosis patients, which is consistent with an antigenic response." (PMID 24339826, 2013). "Despite this lack of homology in position identity among the mycobacterial peptides, 16 sarcoidosis subjects, two PPD- controls and four NTM controls demonstrated CD4+ T cell responses to multiple antigens." (PMID 21092305, 2010). "Together these results reveal that antigen-specific CD4+ and CD8+ T cells responses to multiple mycobacterial epitopes are present within sites of active sarcoidosis involvement, and that these antigen-specific responses are present at the time of diagnosis." (PMID 21092305, 2010). "A CD4/CD8 ratio >3.5, which is a breaking-point for sarcoidosis differential diagnostics, was found in a much greater part of patients with sarcoidosis-related symptoms compared to asymptomatic patients." (PMID 19242869, 2009). "The clinical value of CD4+/CD8+ ratio and of CD8+ positive lymphocytes exists even in cases with normal lymphocytes count and has been already described both in sarcoidosis and in IPF." (PMID 17578573, 2007). "Lymphocyte subsets, especially the CD4/CD8 ratio and activation were previously thought to be helpful in differentiating HP from sarcoidosis." (PMID 16817954, 2006). "A significant correlation was found between CD4+ IFN-γ positive cells in IS and those in BALF in sarcoidosis patients (r = 0.685, p = 0.0006)." (PMID 15978129, 2005). "The aim of this study was to explore induced sputum (IS) CD4+Th1 T-lymphocyte subpopulation and to compare them with those of bronchoalveolar lavage fluid (BALF) in patients with sarcoidosis." (PMID 15978129, 2005). "We also detected a positive correlation between CD4+ IFN-γ producing T cells in induced sputum and those in BALF in sarcoidosis patients (p = 0.0006, r = 0.685)." (PMID 15978129, 2005). "CD4/CD8 ratios are elevated both in vitreous humor and BALF in patients with sarcoidosis." (PMID 39249513, 2025). "Researchers have found that IL-17A-expressing CD4+ T lymphocytes or IL-17A+IFN-γ+ memory T cells and RORγt, a nuclear receptor crucial for the differentiation of Th17 cells, are increased in both the BAL and the peripheral blood of patients with sarcoidosis." (PMID 40724901, 2025). "The CD4/CD8 ratio in bronchoalveolar lavage fluid (BALF) from sarcoid patients is elevated compared to healthy controls, and a significant decrease in the CD4/CD8 ratio is observed along with the radiographic stage of sarcoidosis." (PMID 40217830, 2025). "Additionally, CD4+ T cells from sarcoidosis patients exhibited increased PRDM1 and GATA3 expression, while naive markers SELL, TCF7 and LEF1 were reduced in sarcoidosis and active TU compared with healthy donors." (PMID 40469525, 2025). "BAL showed lymphocytic inflammation with a CD4/CD8 ratio of 7.3, compatible with sarcoidosis." (PMID 41552225, 2025). "GSEA identified enriched ‘TNF alpha signalling via NF‐κB’ and ‘Inflammatory response’ signatures in CD4+ T cells from sarcoidosis, but not active TU patients, compared to healthy donors." (PMID 40469525, 2025). "CD4+ T cell subsets were also similarly represented in patients with active and inactive TU, although we observed a small increase in CD44+ effector cells in the sarcoidosis group compared with healthy donors." (PMID 40469525, 2025). "CD4 was increased in sarcoidosis, while CD8 was increased in non-allergic asthma and amiodarone lung and decreased in sarcoidosis." (PMID 40725075, 2025). "There was no expansion of CXCR5− PD‐1+ CD4+ T cells in active sarcoidosis compared with healthy controls." (PMID 40469525, 2025). "Moreover, CD4 cells expressing PD-1 were higher in our fibrotic cohort (IPF and PCPF patients) than in the sarcoidosis group, suggesting involvement of PD-1 in fibrotic disorders but not granulomatous diseases." (PMID 38540243, 2024).
sarcoidosis (continued). "Using mass cytometry analysis of immune cell subsets in bronchoalveolar lavage fluid (BALF), the analysis of T and B cells revealed increased levels of CXCR3+ CD226+ CD4+ T cells and the presence of FCRL5+ B cells in sarcoidosis patients with advanced lung lesions." (PMID 39896815, 2024). "Although antigen-specific CD4 T cells are thought to play a primary role in sarcoidosis granuloma formation, it is not clear if macrophages from sarcoidosis patients are intrinsically prone to form granulomas." (PMID 38353578, 2024). "Clinically, a CD4/CD8 ratio > 3.5 and lymphocytosis >15% support the diagnosis of sarcoidosis." (PMID 38804438, 2024). "Sarcoidosis unique upregulated DEGs in response to LPS were FOXP1 (Forkhead Box P1), DDIT4 (DNA Damage Inducible Transcript 4), and IL7R, and unique downregulated DEGs in sarcoidosis were PYCARD (Caspase Recruitment Domain-Containing Protein 5), CD4, and PLD3 (Phospholipase D Family Member 3)." (PMID 39284999, 2024). "Nevertheless, several factors may impact on CD4/CD8 ratio, such as active smoking, obstructive pulmonary disease, more advanced stages of sarcoidosis, and treatment." (PMID 39062076, 2024). "Macrophages and CD4 T-lymphocytes express glucose transporters on the cell membrane that allow substrates such as FDG to enter cells, which contributes to granulomatous inflammation in sarcoidosis." (PMID 39598118, 2024). "We observed lower percentages of CD4+- and CD8+-TIGIT+ in sarcoidosis patients than in our fibrotic groups, IPF and PCPF, suggesting that the latter disorders may express a higher degree of exhaustion of T cells." (PMID 38540243, 2024). "Some EV markers were common between HP and sarcoidosis (CD11c, CD1c, CD209, CD4, CD40, CD44, CD8)." (PMID 36835481, 2023). "Increased levels of CD4+ T-cells producing IFN-y were found in lung lavage and increased levels of IFN-y induced chemokines were observed in serum from patients with sarcoidosis." (PMID 36830609, 2023). "Measurement of PB Tregs, Ki-67+CD4+ and Ki-67+CD8+ T cells may help in predicting sarcoidosis disease course." (PMID 38097354, 2023). "On the other hand, lymphocytosis is not specific to sarcoidosis, being found in many other diseases such as tuberculosis or pulmonary mycosis, especially in the context of a CD4/CD8 ratio below 3.5." (PMID 36672683, 2023). "Sarcoidosis and HTLV-1 infection both affect T cell function, especially CD4+ T cells, and may developped the patient’s PML." (PMID 36726087, 2023). "Given that activated CD4+ and CD8+ T cells contribute to the pathophysiology of inflammatory diseases including MS, RA, sarcoidosis, and autoimmune uveitis, inhibition of T cell activity may lead to improved outcomes in patients with these diseases." (PMID 37062818, 2023). "However, in patients with sarcoidosis, BAL allows the demonstration of CD4+ T-cell lymphocytic alveolitis." (PMID 37250639, 2023). "Using CD4/CD8 ratio > 3.5 increases specificity for sarcoidosis to 93–96% but still does not have high sensitivity (53 to 59%)." (PMID 37721575, 2023). "To examine the absolute and relative numbers of main peripheral blood T cell subsets, including T cells, Th cells, CD8+ T cells, and regulatory T cells (Tregs), in patients with sarcoidosis, we analyzed CD3, CD4, CD8, CD25, and CD127 expression by flow cytometry." (PMID 37189479, 2023). "We speculate that CD4 T cells migrating to the lungs through CXCR3 may be activated through CD226, potentially contributing to the pathogenesis of sarcoidosis." (PMID 36949950, 2023). "The authors of the cryptOsarc study even considered that “the CD4 levels in this study did not explain cryptococcosis in sarcoidosis”." (PMID 35425769, 2022). "Th17-dominant CD4-positive T cells are abundant in BALF and granulomatous lesions of sarcoidosis." (PMID 35744031, 2022).
sarcoidosis (continued). "Moreover, results showed that BALF total autoantibodies concentrations were higher in patients with sarcoidosis than in controls and that BALF AVAs concentrations of patients with sarcoidosis were positively correlated with CD4+ T-cells clonal expansion." (PMID 36148452, 2022). "Although our study confirmed this in our sarcoidosis population, a higher CD4/CD8 ratio was observed in lymph node tissue than in peripheral blood." (PMID 35629428, 2022). "Sarcoidosis is pathologically characterized by non-caseating granulomas surrounded by numerous immune cells, including CD4+ and CD8+ T lymphocytes and a small number of B lymphocytes." (PMID 35615369, 2022). "Interestingly, patients with sarcoidosis and autoantibodies showed higher levels of erythrocyte sedimentation rate (ESR), globulins, and CD4 cells in BALF, as well as a more advanced age compared to patients with sarcoidosis without autoantibodies." (PMID 36148452, 2022). "In this study, the CD4/8 ratio in the BALF was significantly higher in the past-tumor group than in the non-past-tumor group in patients with sarcoidosis." (PMID 35744031, 2022). "CINS patients with sarcoidosis have a similar clinical and biological presentation at diagnosis but exhibit a higher CD4/CD8 T cells ratio than those without sarcoidosis." (PMID 35425769, 2022). "In order to better understand how JAK inhibition might control inflammation in sarcoidosis beyond inhibition of IFN-γ, we returned to the IPA analysis comparing CD4+ SAR-1 cells to CD4+ CTRL cells." (PMID 35668129, 2022). "Notwithstanding, our independent analysis determined that a CD4+ T-cell count of ≤ 524.5 cells/μL is related to PET positivity and note that this was comparable to threshold levels previously utilized to assess major organ involvement in sarcoidosis." (PMID 33718397, 2021). "The most common finding of histopathology in sarcoidosis is the classic non-necrotizing granulomas with a central area of multinucleated giant cells, macrophages, CD4-positive T lymphocytes, and epithelioid cells." (PMID 34540506, 2021). "To further evaluate the associations between the nuclear morphological parameters of BALF lymphocytes and the clinical features of sarcoidosis, we investigated the correlation between the BALF CD4/CD8 ratio and the fraction of lymphocytes with small and round nuclei in sarcoidosis patients." (PMID 34217348, 2021). "However, peripheral reductions in lymphocytes, specifically CD4+ T-cells, were significantly related to inflammation identified on 18FDG-PET/CT and therefore sarcoidosis activity." (PMID 33718397, 2021). "However, in sarcoidosis patients both serum and BALF levels of KL-6 correlate with higher serum ACE levels and CD4+/CD8+ ratio." (PMID 32760396, 2020). "One of the individuals with a high expression in BALF was a healthy control without signs of sarcoidosis or any other pulmonary disease on chest X-ray, but with a CD4/CD8-ratio of 4.4." (PMID 32111204, 2020). "An increased proportion of CD4 + helper T-cells with an elevated CD4/CD8 ratio in BAL fluid, detected in a high proportion of our patients, has a specificity of ~ 95% for sarcoidosis, although the sensitivity is slightly below 60%." (PMID 32740881, 2020). "In fact, higher percentages of CD4+ T-cells expressing Programmed Death-1 (PD-1), an inhibitory receptor that negatively regulates proliferation, cytokine secretion and survival of CD4+ T-cells, were found in BAL fluid and peripheral blood of patients with sarcoidosis." (PMID 33036432, 2020). "Additionally, peripheral blood of sarcoidosis patients had increased numbers of CD62L+ CD45RA− CD45RO+ central memory and CD62− CD45RA− CD45RO+ effector memory CD4+ T-cells with significantly decreased numbers of CD62L+ CD45RA+ CD45RO− naïve CD4+ T-cells." (PMID 33036432, 2020).